MTOR (mechanistic target of rapamycin kinase)
Diseases named in the same sentence as MTOR in open-access papers (continued):
Sharing a sentence is not in itself a finding about the gene and the disease.
ovarian hyperstimulation syndrome (1 paper, 2024). A complication of ovulation induction in infertility treatment. "The potential reproductive benefits of mTOR inhibitors include decreased miscarriage rates, improved implantation, and prevention of age-related follicular loss and ovarian hyperstimulation syndrome." (PMID 39579091, 2024). "In vivo studies have also suggested that mTOR inhibitors may prevent ovarian hyperstimulation syndrome (OHSS) by controlling immune responses and VEGF-mediated angiogenesis." (PMID 39579091, 2024).
pancreatic diseases (1 paper, 2024). "The mTOR pathway is closely related to the proliferation, differentiation, apoptosis, motility, metabolism and autophagy of cells, and the regulation of this pathway contributes to the precision treatment of pancreatic diseases." (PMID 38358010, 2024).
papillary renal cell carcinoma (1 paper, 2022). A rare subtype of renal cell carcinoma, arising from the renal tubular epithelium and showing a papillary growth pattern, which typically manifests with hematuria, flank pain, palpable abdominal mass or nonspecific symptoms, such as fatigue, weight loss or fever. "And a study of papillary renal cell carcinoma demonstrated that phosphorylates Akt (p-Akt) and phosphorylates mTOR (p-mTOR) were inhibited by the suppression of PYCR1." (PMID 35371311, 2022). "The result indicated that PYCR1 may regulate the progression of papillary renal cell carcinoma through the Akt/mTOR pathway 20,22." (PMID 35371311, 2022).
parathyroid adenomas (1 paper, 2021). "However, TSC mutations could also lead to parathyroid adenoma development in an mTOR-independent pathway." (PMID 34025587, 2021). "However, recent advances in understanding the biology and pathogenesis of parathyroid adenomas do not seem to involve the mTOR pathway." (PMID 34025587, 2021).
pharyngeal cancer (1 paper, 2020). "Whole genomic expression analysis of the E2/E4/E5 pharyngeal cancer subtype is defined by activation of the fibroblast growth factor receptor (FGFR) pathway and this subtype is susceptible to combination FGFR and mTOR inhibition, with implications for targeted therapy." (PMID 32848210, 2020).
phyllodes tumor (1 paper, 2013). A benign, borderline, or malignant fibroepithelial neoplasm arising from the breast and rarely the prostate gland. "We describe for the first time an NRAS mutation with concomitant activation of PI3K/Akt/mTOR in phyllodes tumor." (PMID 23895135, 2013).
pituicytoma (1 paper, 2018). An extremely rare, WHO grade I, circumscribed and slow-growing tumor that arises from the neurohypophysis or infundibulum and described in adults. "ChG and pituicytomas share several similarities such as TTF1 expression and mTor pathway activation." (PMID 29915258, 2018).
placental disorders (1 paper, 2020). "Thus, changes in CCN3 levels alter the expression of senescence markers and the FAK-Akt-mTOR pathway in placental disorders with reduced or increased the proliferation and/or differentiation of CTB." (PMID 33304321, 2020).
plasmacytoma (1 paper, 2014). Plasmacytoma is a localized mass of neoplastic monoclonal plasma cells that represents approximately 5% of all plasma cell neoplasms. "As mentioned by Peterson, it is notable that development of plasmacytomas in mice is facilitated by genetic loss of mTOR function, suggesting mTORC1 can be a tumor suppressor in the MM model." (PMID 25568666, 2014).
polydactyly (1 paper, 2024). A disease characterized by the presence of polydactyly, including syndromic and non-syndromic forms. "Because of the co-occurrence of macrocephaly and polydactyly, a combination of phenotypes often observed in mTOR hyperactivation disorders, which result in CCND2 stabilization, we hypothesized that the MAXArg60Gln variant may also result in CCND2 stabilization." (PMID 38141607, 2024).
polymyositis (1 paper, 2017). A rare idiopathic inflammatory myopathy characterized by symmetric proximal muscle weakness and elevated muscle enzymes. "In this study, we aim to figure out the role of mTOR signaling in the development of polymyositis and identify novel biomarkers for the detection and therapy of polymyositis." (PMID 28194428, 2017).
proliferative diabetic retinopathy (1 paper, 2011). Advanced retinopathy due to diabetes mellitus characterized by the formation of new vessels in the retina. "Therefore, several growth factors that have demonstrated a role in the development of the vasculopathy characteristic of human proliferative diabetic retinopathy are linked to the PI3K/Akt/mTOR pathway for the regulation of their expression and activity." (PMID 22132311, 2011).
proliferative vitreoretinopathy (1 paper, 2025). Vitreoretinal membrane shrinkage or contraction secondary to the proliferation of primarily retinal pigment epithelial cells and glial cells, particularly fibrous astrocytes, followed by membrane formation. "The Akt/mTOR pathway is implicated in TGF‐β‐promoted pericyte‐myofibroblast transition subretinal fibrosis, and suppressed GSK3β expression and activated PI3K/Akt signaling have been observed in proliferative vitreoretinopathy models." (PMID 41147690, 2025).
psychosis (1 paper, 2021). "Future studies may seek to validate this mechanism of both CBD and CBG in models of MS and psychosis and for the treatment of other mTOR‐dependent conditions." (PMID 33347604, 2021).
Pulmonary bulla (1 paper, 2025). Pulmonary bullae are rounded focal regions of emphysema with a thin wall which measure more than 1 cm in diameter. "The grayscale value of positive cells of p-mTOR (mTOR signaling pathway) in Birt–Hogg–Dubé patients was lower than in patients with simple pulmonary bulla (98.000 ± 1.630 vs. 67.800 ± 2.209)." (PMID 40677928, 2025). "The grayscale value of positive cells of β-catenin (mTOR signaling pathway) in Birt–Hogg–Dubé patients was lower than in patients with simple pulmonary bulla (66.467 ± 1.142 vs. 114.933 ± 1.307)." (PMID 40677928, 2025). "The results showed that the positive rates of p-Smad3 and p-mTOR were higher in Birt–Hogg–Dubé patients compared with simple pulmonary bulla patients, and β-catenin was lower in Birt–Hogg–Dubé patients compared with simple pulmonary bulla patients." (PMID 40677928, 2025).
Pulmonary hemorrhage (1 paper, 2012). Pulmonary hemorrhage is a bleeding within the lungs. "Current mTOR inhibitor inclusive regimens may account for decreased number of tumors in kidney transplant recipients but also carry a risk of pulmonary toxicity manifesting histologically by pulmonary hemorrhage, organizing pneumonia and other less common histological patterns." (PMID 22416975, 2012).
rectal adenocarcinoma (1 paper, 2024). "However, inhibition of mTOR could prolong the G0/G1 phase of the cell cycle and reduce DNA damage repair efficiency via attenuation of homologous recombination, which suggests that mTOR might play important roles in the radiosensitivity of rectal adenocarcinoma cells." (PMID 38741069, 2024). "It was found that ionizing radiation could induce sustained activation of mTOR and promote the levels of pS6, p-4E-BP1 and p-Akt473 in rectal adenocarcinoma cells (not published)." (PMID 38741069, 2024).
renal adenoma (1 paper, 2012). An adenoma arising from the renal cortex. "The complete absence of p-S6 staining in the three small renal adenomas found in rats over two years old (OTA given only in the second year) may be demonstrating that genetic or epigenetic events associated with mTOR pathway dysregulation is a later step associated with progression to carcinoma." (PMID 23105973, 2012).
renal oncocytoma (1 paper, 2023). "In this morphological scenario, cathepsin-K (clone 3F9) is a useful tool for differentiating renal oncocytoma, chromophobe RCC, and LOT which are negative for cathepsin-K (clone 3F9), from ESC-RCC, EVT, and mTOR-mutated eosinophilic RCC which are positive for this marker." (PMID 37938323, 2023).
respiratory syncytial virus infection (1 paper, 2023). "QF may alleviate inflammation induced by respiratory syncytial virus infection in asthmatic mice by inhibiting autophagy through mTOR pathway." (PMID 37090692, 2023).
Retinal dysplasia (1 paper, 2017). Abnormal growth and differentiation, structure and appearance of the retina present from birth. "Pathway analyses suggested a decrease in cellular respiration and increased expression of components of Hif1-α, VEGF, mTOR, NFκβ, and multiple interleukin pathways are associated with early retinal dysplasia." (PMID 28192065, 2017). "In summary, differential gene expression and cytological analyses of retinal dysplasia in adult Tg(flk1:RFP)is18/+ zebrafish predisposed to optic pathway tumors reveal that ectopic proliferation is associated with elevated expression of markers in the VEGF, Leptin, and mTOR pathways." (PMID 28192065, 2017).
retinal tumors (1 paper, 2017). "Compared to VEGF and Leptin signaling, mTOR activation may not be a factor in initiating inappropriate proliferation in the early dysplastic retina, but could contribute to the sustained growth of retinal tumors." (PMID 28192065, 2017).
retinitis (1 paper, 2019). Inflammation of the retina. "Rapamycin treatment increased the levels of LC3B-II by inhibiting mTOR and decreased the levels of cleaved caspase-3 during MCMV retinitis." (PMID 31291924, 2019). "Taken together, these results suggest that the activation of mTOR pathway and the induction of caspase 3-dependent apoptosis are involved in the process of MCMV retinitis." (PMID 31291924, 2019).
retinitis pigmentosa (1 paper, 2022). Retinitis pigmentosa (RP) is an inherited retinal dystrophy leading to progressive loss of the photoreceptors and retinal pigment epithelium and resulting in blindness usually after several decades. "In an rd1 mouse model of retinitis pigmentosa, mTOR was upregulated in photoreceptors." (PMID 35883796, 2022).
Rickettsia infection (1 paper, 2020). "The results suggest increased phosphorylation of p70 S6K and mTOR during Rickettsia infection of ECs as early as 3 h and persisting for up to 24 h post-infection." (PMID 33003310, 2020).
salivary gland mucoepidermoid carcinoma (1 paper, 2021). A carcinoma that arises from the salivary glands. "Collectively, these results suggest that patients with salivary gland mucoepidermoid carcinoma might benefit from therapeutic inhibition of the mTOR pathway." (PMID 33479203, 2021). "Collectively, these data demonstrated that mTOR signaling is required for CSC survival, and unveiled the therapeutic potential of targeting the mTOR pathway for elimination of highly tumorigenic cancer stem-like cells in salivary gland mucoepidermoid carcinoma." (PMID 33479203, 2021).
sebaceous carcinoma (1 paper, 2022). "For sebaceous carcinoma, tumor sequencing revealed RAR-β, androgen receptor, mTOR, and EGFR as the potential investigational approaches." (PMID 35205753, 2022).
Senile plaques (1 paper, 2021). Senile plaques are extracellular deposits of amyloid in the gray matter of the brain. "Chronic activation of unrestrained mTOR could be responsible for sustaining metabolic dysfunction that causes the breakdown of the blood-brain barrier, tau hyperphosphorylation and senile plaques formation in AD." (PMID 34069618, 2021).
Shock (1 paper, 2025). The state in which profound and widespread reduction of effective tissue perfusion leads first to reversible, and then if prolonged, to irreversible cellular injury. "In summary, this study revealed the critical involvement of the IL-6/JAK/STAT3, PI3K/Akt/mTOR, and TNF-α/NF-κB pathways in pediatric postoperative septic shock and identified key genes such as PIM3, with quercetin and astramembrannin I predicted as potential therapeutic compounds." (PMID 41189212, 2025).
sialidosis (1 paper, 2021). "Unstimulated basal levels of autophagic vacuoles were not detectable in either normal- or sialidosis-iNPCs by the CYTO-ID autophagy detection assay; thus, we evaluated the impact of rapamycin, an mTOR-dependent autophagy inducer, in the sialidosis-iNPCs and compared them to normal-iNPCs (green)." (PMID 33922276, 2021).
skull base meningioma (1 paper, 2020). A meningioma that arises from the skull base. "Subsequently, to better mimic clinical conditions of skull-base meningiomas, we implanted tumor cells at the skull base and treated mice with the mTOR inhibitor Temsirolimus." (PMID 32245394, 2020).
small bowel cancer (1 paper, 2022). "Previous studies have proved the prominent mutations of MTOR and functions of mTOR signaling in small bowel cancer." (PMID 35397555, 2022). "The mutation of MTOR was the driven mutation for small-bowel carcinoma, and is regarded as the potential targets in the clinic." (PMID 35397555, 2022).
spinal cord ischemia (1 paper, 2023). Reduced blood flow to the spinal cord which is supplied by the anterior spinal artery and the paired posterior spinal arteries. "GBP can activate the PI3K/Akt/mTOR signaling pathway, which may explain the reduction of oxidative stress after GBP administration in the spinal cord ischemia-reperfusion injury model." (PMID 36835284, 2023).
spinocerebellar ataxia type 1 (1 paper, 2017). Spinocerebellar ataxia type 1 (SCA1) is a subtype of type I autosomal dominant cerebellar ataxia (ADCA type I) characterized by dysarthria, writing difficulties, limb ataxia, and commonly nystagmus and saccadic abnormalities. "Moreover, ATXN1 regulates the cerebellar bioenergetics proteome through the GSK3b-mTOR pathway, which is altered in spinocerebellar ataxia type 1 (SCA1), an autosomal dominant neurodegenerative disorder." (PMID 29212253, 2017).
staphylococcus aureus pneumonia (1 paper, 2022). An pneumonia caused by infection with Staphylococcus aureus. "Staphylococcus aureus pneumonia and virulence factor A can stimulate the AMPK signaling pathway and inhibit the mTOR pathway to induce autophagy in alveolar epithelial cells, an important mechanism during early infection of S. pneumoniae." (PMID 35340244, 2022).
Stargardt disease (1 paper, 2024). "In the Abca4−/− mouse model of Stargardt disease, increased RPE cell endocytosis of complement factor C3a resulted in increased mTOR activation." (PMID 38920696, 2024).
Still’s disease (1 paper, 2022). "Single-cell RNA sequencing in a murine model of Still’s disease shows preferential activation of mTORC1 in monocytes; both mTOR inhibition and monocyte depletion attenuate disease severity." (PMID 36443301, 2022).
streptococcus pneumonia (1 paper, 2021). "In summary, the QFY anti-streptococcus pneumonia effect appears to be associated with activation of autophagy through down-regulation of upstream autophagy pathway events involving NLRP3/mTOR." (PMID 35111047, 2021).
structural epilepsy (1 paper, 2021). A type of epilepsy that is conceptualized as having a distinct structural brain abnormality that has been demonstrated to be associated with a substantially increased risk of epilepsy in appropriately designed studies. "Apart from tuberous sclerosis complex, the involvement of the mTor pathway in structural epilepsy was shown in several animal models, including chronic models induced by kainate and pilocarpine." (PMID 33859552, 2021).
sudden infant death syndrome (1 paper, 2021). Unexpected death in infancy which remains unexplained following autopsy, review of the medical history, and investigation of the death circumstances and death scene. "SS fibroblasts exhibited down-regulation of VEGFA, affecting other WikiPathways (the endothelin, PodNet: protein-protein interactions in the podocyte pathways as well as the PI3K-Akt signaling/focal adhesion-PI3K-Akt-mTOR-signaling and the sudden infant death syndrome (SIDS) Susceptibility pathways." (PMID 33669496, 2021).
syringomyelia (1 paper, 2018). Syringomyelia is characterized by cerebrospinal fluid (CSF)-filled cavities (syrinx) inside the spinal cord, either as a result of a known cause (secondary syringomyelia, SS) or, more rarely, due to an unknown cause (primary syringomyelia, PS). "Enhanced mTOR activity reduces death of motor neurons, protects the damaged nerve tissue, reduces formation of syringomyelia after SCI and contributes to repair." (PMID 30505267, 2018).
systemic vasculitis (1 paper, 2024). "Our findings reveal that luminal myofibroblasts develop from SMCs and their formation (in multiple forms of systemic vasculitis) is driven by activation of the mechanistic target of rapamycin (mTOR) signalling pathway." (PMID 39271773, 2024). "We believe these findings provide a compelling rationale for clinical trials of mTOR inhibitors as a novel therapeutic strategy in systemic vasculitis." (PMID 39271773, 2024). "Moreover, our findings that mTOR is activated in the luminal myofibroblasts of patients with KD, GCA and TAK, imply that mTOR inhibition may be more widely effective in systemic vasculitis." (PMID 39271773, 2024).
telomere syndrome (1 paper, 2020). Accelerated aging syndromes often caused by inheritable gene mutations resulting in decreased telomere lengths. "This is of relevance as mTOR inhibitors could represent potential treatments for human patients suffering from telomere syndromes." (PMID 32127537, 2020).
testicular dysfunction (1 paper, 2022). "Indeed, the involvement of AMPK/mTOR stimulation has been described to attenuate cadmium-evoked testicular dysfunction." (PMID 35890148, 2022).
Testicular torsion (1 paper, 2024). Testicular torsion is when the spermatic cord to a testicle twists, cutting off the blood supply. "Eprosartan hold promise for managing testicular dysfunction arising from testicular torsion exerting antioxidant, pro-autophagic and anti-apoptotic effect via the activation of SIRT1/Nrf2/HO-1 as well as Beclin-1/AMPK/mTOR pathways." (PMID 38822026, 2024).
Thrombocytosis (1 paper, 2025). Increased numbers of platelets in the peripheral blood. "Collectively, these mechanisms converge to sustain aberrant PI3K/AKT/mTOR activation, leading to excessive megakaryopoiesis and pathological thrombocytosis in patients carrying such mutations." (PMID 41438978, 2025).
thymic tumors (1 paper, 2025). "Especially, everolimus, an mTOR inhibitor targeting the PI3K-mTOR pathway, has been demonstrated to have therapeutic value in phase II clinical studies of thymic tumors." (PMID 41388389, 2025).
toxicity (1 paper, 2022). The degree to which an agent can damage an organism. "Meanwhile, mTOR inhibitors are an alternative ISD regularly used after SOT to replace or minimize CNIs, especially in cases of malignancies or of CNI-related renal toxicity." (PMID 35757737, 2022).
transitional cell papilloma (1 paper, 2023). A benign papillary neoplasm composed of transitional cells which show preservation of the nuclear polarity. "The effect of hAM homogenate and extract on the expression of genes and proteins involved in the PI3K/Akt/mTOR pathway was somewhat different in transitional cell papilloma RT4 cells." (PMID 37932474, 2023).
trigonocephaly (1 paper, 2022). "Levels of p‐AKT, p‐mTOR and p4EBP1 were increased in trigonocephaly cells with IgPKD1 compared to mock cells (p < 0.001)." (PMID 35285136, 2022). "Immunoblotting analysis showed a notable reduction of p‐mTOR, p‐4EBP1 and p‐AKT expression in PI3K‐inhibited cells in both trigonocephaly and dolichocephaly cranial suture cells." (PMID 35285136, 2022).
type 2 diabetic nephropathy (1 paper, 2016). "Collectively, these findings showed AS-IV to be beneficial to type 2 diabetic nephropathy, which might be associated with the inhibition of Akt/mTOR, NFκB and Erk1/2 signaling pathways." (PMID 27585918, 2016).